MMP9 (matrix metallopeptidase 9)
Diseases named in the same sentence as MMP9 in open-access papers (continued):
Sharing a sentence is not in itself a finding about the gene and the disease.
ovarian carcinoma (continued). "SAHA treatment induced apoptosis and reduced migration, invasion and lamellipodia formation in the ovarian carcinoma cells; furthermore, SAHA decreased expression of Cyclin B1 and CDC2P34 mRNA, and downregulated CDC2P34, Erk1/2, CyclinB1 and MMP-9 proteins." (PMID 24236158, 2013). "AXL protein expression was found to be significantly higher in ovarian carcinomas than in ovarian epithelium, and knockdown of AXL in SKOV3 cells also reduced the expression of MMP-1 and MMP-9, which contribute to tumour cell invasion." (PMID 23878800, 2013). "In ovarian cancer, MMP-9 is expressed in both the stroma and the ovarian epithelial tumor cells and MMP-9 expression in either compartment is indicative of poor prognosis." (PMID 23340649, 2013). "To study the effect of minocycline on MMP activity in ovarian cancer cells, we analyzed the expression of MMP-2 and MMP-9 in SKOV-3 cells after treatment with varying concentrations of minocycline for 18 h." (PMID 23593315, 2013). "We therefore, used a translational approach to analyze the epithelial and stromal expressions of MMP-2, MMP-7, MMP-9, MT1-MMP, TIMP-1 and TIMP-2 in advanced epithelial ovarian cancers and to assess their prognostic value." (PMID 22200690, 2012). "About 15 studies have been published on the prognostic value of MMP-2, MMP-7, MMP-9, MT1-MMP, TIMP-1 or TIMP-2 in ovarian cancers, but the results remain controversial." (PMID 22200690, 2012). "We set out to analyze the epithelial and stromal expression of MMP-2, MMP-7, MMP-9, MT1-MMP, TIMP-1 and TIMP-2 in advanced epithelial ovarian cancers and to assess their prognostic value." (PMID 22200690, 2012). "High levels of MMP-9 have been found in human ovarian carcinoma xenografts and overexpression of MMP-7 in ovarian cancer cell lines and cancer surgical specimens." (PMID 22200690, 2012). "For pre-treatment ovarian cancer patients, the median VEGF and MMP-9 protein concentrations were 609.1 pg/ml (range, 43.2-1845.2 pg/ml) and 404.3 ng/ml (range, 35.9-1623.6 ng/ml), respectively." (PMID 20334653, 2010). "Plasma concentrations of VEGF and MMP-9 and circulating EPC levels were correlated in pre-treatment ovarian cancer patients (P < 0.01)." (PMID 20334653, 2010). "Studies in ovarian carcinoma cells have shown that FAK and ERK1/2 are important for fibronectin-stimulated invasiveness and MMP9 secretion by these cells." (PMID 19568240, 2009). "Ovarian cancer cells express MMP2 and MMP9, and we and others have shown that increased expression of MMPs is associated with cancer cell invasiveness and metastatic potential." (PMID 17567918, 2007). "Induces apoptosis in ovarian cancer cells through caspase- and ROS-dependent pathways; reduces recruitment of TAMs by inhibiting chemokines MCP-1 and RANTES; suppresses M2 polarization of TAMs and reduces cancer-promoting factors like MMP-2, MMP-9, and VEGF." (PMID 40330466, 2025). "The association between RBP4 and tumor size suggests that RBP4 may promote tumor growth, as also described in ovarian cancer, where RBP4 enhances migration and proliferation by activating RhoA/Rock1 and ERK pathways and upregulating MMP2 and MMP9." (PMID 41007818, 2025). "The results indicated that Kirenol has the potential to inhibit metastasis, as shown by its ability to reduce the migratory capacity of ovarian cancer cells and decrease the expression of key factors involved in cell migration and invasion, including MMP-2 and MMP-9." (PMID 38415456, 2025). "Tumor-derived MMP2 and MMP9 expression has been identified as a negative prognostic indicator in ovarian cancer patients, predicting lower overall survival rates." (PMID 40558552, 2025). "Exposure of cervical cancer cells (HeLa) to CP reduced ERK1/2 and JNK activity, while JNK and p38 activity was reduced in ovarian cancer cells exposed to PAM, leading to significantly diminished invasiveness (cell migration) and matrix metalloproteinase 9 (MMP9) activity." (PMID 38785562, 2024).
ovarian carcinoma (continued). "Since matrix metalloproteinase 9 (MMP9) and MMP2 are upregulated in ovarian cancer and their activity is correlated with invasion and metastasis, we hypothesized that the impact of LKB1 and STRADα on EOC invasion is mediated by MMP activity." (PMID 39594681, 2024). "Moreover, we analyzed the Cancer Genome Atlas Ovarian Cancer (TCGA-OV) database, and found CD68+YAP1low groups exhibited dramatically increased M2-like TAMs markers expression, such as MMP9, CCL8, SPP1 and CCL17, when compared to CD68+ YAP1high." (PMID 39198883, 2024). "MMP-9 is an unfavorable prognostic factor in HNC, bladder cancer and ovarian cancer, which might indicate its key role in angiogenesis." (PMID 37226100, 2023). "To investigate whether our in vitro experimental results are consistent with the pathogenesis of ovarian cancer, we examined the expression of MICALL2 and MMP9 in ovarian cancer and adjacent tissues using a microarray (30 paired cases)." (PMID 38203692, 2023). "Therefore, RAD21 likely promoted the progression of ovarian cancer by regulating the expression of MMP2 and MMP9, and its high expression predicted poor prognosis of ovarian cancer patients." (PMID 35860572, 2022). "Additionally, the positive correlation between HK2 and fibronectin, MMP9, CHD2, Vimentin, ZEB1 and ZEB2 in human ovarian cancer were confirmed from the GEPIA online database (p < 0.05)." (PMID 35953860, 2022). "In ovarian cancers, activation of EGFR activation stimulates signalling cascades which could lead to increased expression of MMP‐9 and MT1‐MMP." (PMID 36448260, 2022). "Additionally, the positive correlation between HK2 and fibronectin, MMP9, CHD2, Vemintin, ZEB1 and ZEB2 in human ovarian cancer were also confirmed from the GEPIA online database." (PMID 35953860, 2022). "In addition, transcriptome analysis of the ovarian cancer cell line SKOV3 showed similar results for cell adhesion molecules, growth factors, and MMP9, thereby confirming previous results." (PMID 35954423, 2022). "Thus, to inhibit ovarian cancer cell invasion, it is important to regulate the activation and expression levels of MMP2 and MMP9." (PMID 35621926, 2022). "Moreover, SLT significantly inhibited the protein levels of MMP2, MMP9, and N-cadherin, and increased the protein level of E-cadherin, indicating that SLT can inhibit EMT in ovarian cancer cells." (PMID 33869638, 2021). "Norepinephrine can increase the expression of VEGF in ovarian cancer cells and promote the migration of endothelial cells by inducing the expression of MMP-2 and MMP-9, thereby inducing the formation of new blood vessels in tumors." (PMID 34307378, 2021). "For example, MMP-2 mRNA expression was significantly higher in ovarian cancer cells that was sensitive to chemotherapy compared with resistant/refractory tumors, while no significant change in MMP-9 mRNA expression was noted." (PMID 35047406, 2021). "Moreover, ADSCs stimulate ovarian cancer cell proliferation and metastasis by producing MMP2 and MMP-9 proteins." (PMID 34440886, 2021). "miR-9 inhibits the expression of extracellular signal-regulating kinases ERK1, ERK2, and MMP-9 by inhibiting the CXCR4-CXCL12 signaling pathway, and the long-chain noncoding RNA LSLINCT5 also plays an important role in ovarian cancer metastasis by regulating the CXCR4-CXCL12 signaling pathway." (PMID 33829065, 2021). "The expression of MMP-9, but not MMP-2, was associated with ERK activation and cancer invasion by CCL7 in human ovarian cancer cells." (PMID 34206004, 2021). "Considering the well-characterized role of MMP-9 and MMP-2 in the metastases of many cancers, including ovarian cancer, we investigated whether CCL7-induced ERK activation mediated the expression of these enzymes." (PMID 34206004, 2021). "Given the well-defined roles of E-cadherin, N-cadherin, TGFβ and MMP-9 in invasion and EMT regulation, we evaluated if polβ could influence the expression of these key EMT markers in ovarian cancer cells." (PMID 33674744, 2021).
ovarian carcinoma (continued). "Our results showed that miR-367 inhibited the expression of MCM2, MMP2, MMP9, and VEGF, suggesting that miR-367 may repress tumor cell proliferation, migration, invasion, and angiogenesis in ovarian cancer." (PMID 33024414, 2020). "The top 5 related genes are TBP, MMP9, MYC, MAPK1, MTOR, which might play important roles in ovarian cancer." (PMID 32958005, 2020). "Previous studies have described the expression of MMPs in epithelial ovarian cancer and evaluated the presence of MMP-2 and MMP-9 in the tumor as potential biomarkers of aggressiveness of the malignancy, registering the disease-free period and the overall survival of patients." (PMID 32718331, 2020). "Clinical, in vitro and in vivo evidence strongly suggested that upregulation of HK2 in ovarian cancer was correlated with metastasis and poor survival and mediated migration, invasion and stemness via PTK2/MAPK1/3/MMP9/NANOG/SOX9 signaling cascades in vitro and in a nude mouse model." (PMID 33052246, 2020). "Furthermore, overexpression of MMP‐2 and MMP‐9 was observed in ovarian cancer, and knockdown of both MMP proteins diminished the cell invasiveness of ovarian cancer." (PMID 32893977, 2020). "Our results indicated that the knockout of the EGFL6 gene could inhibit EMT in ovarian cancer cells by upregulating the expression of E-cadherin and downregulating the expression of N-cadherin, MMP2, MMP9, and Vimentin." (PMID 32983976, 2020). "Tregs from ovarian carcinoma patients express high levels of CCR5, and treatment with conditioned medium from ovarian carcinoma stem-like cells increases their expression of IL-10 and MMP-9." (PMID 32630699, 2020). "MMP-2 and MMP-9 activity was detected in cervical, breast and ovarian carcinoma and ascites of patients with epithelial ovarian cancer (EOC) but not in the serum of these patients." (PMID 32581215, 2020). "Late passage was found to increase metastatic activity but not invasion through Matrigel®, and late passage of human ovarian carcinoma cells increased MMP-9 but not MMP-2 expression." (PMID 31489536, 2020). "Similarly, elevated NE levels enhance the invasive potential of ovarian cancer cells most likely due to higher expression levels of MMP-2 and MMP-9." (PMID 33392191, 2020). "In addition, it inhibits the cancer-promoting factors, including VEGF, MMP9, MMP2, and IL-10, in macrophages stimulated by ovarian cancer cells." (PMID 30871059, 2019). "Furthermore, in an in vivo ovarian cancer xenograft model, omental adipose-derived MSCs were found to promote the formation of peritoneal metastasis via the upregulation of MMP-2 and MMP-9 expressions." (PMID 30568223, 2019). "However, a disaffinity was revealed in that when treating ovarian cancer cell lines with a PI3K inhibitor, LY294002, a reduction in gonadotropin-induced MMP-2 activity but with little change in MMP-9 activity was noted." (PMID 31295843, 2019). "It indicated that MMP9, Bcl2, and caspase 3 may play roles on TRIM52-mediated regulation in ovarian cancer cells invasion, migration, and apoptosis." (PMID 30185771, 2018). "In addition, LPA upregulates MMP-9 which also contributes to E-cadherin ectodomain shedding, contributing to EMT in ovarian cancer cells." (PMID 29393911, 2018). "In addition, DR6 enhanced ovarian carcinoma cell migration ability, and decreased expression of DR6 inhibited the expression of matrix metalloprotease (MMP) 2 and MMP9, and increased the expression of E‐cadherin." (PMID 30186750, 2018). "However, another study on ovarian cancer showed that β4-integrin depletion reduced the expression of MMP-2 and MMP-9, consistent with our data." (PMID 29190919, 2017).
ovarian carcinoma (continued). "HIF‐1α binds to AEG‐1 promoter and induces upregulated AEG‐1 expression to enhance metastasis in ovarian cancer by increasing MMP2 and MMP9 expression as well as attenuating E‐cadherin and β‐catenin expression during hypoxia, which is a typical feature of tumor microenvironment." (PMID 28401704, 2017). "Western blot showed that miR-519d transfection in ovarian carcinoma cells downregulated RhoC (Ras homolog gene family member C), Bcl-2, cyclin D1, survivin, MMP2, MMP9, STAT3 (signal transducer and activator of transcription 3), and HuR (ELAV-like RNA-binding protein 1) expression (P < 0.05)." (PMID 28146423, 2017). "In this study, we assessed the impact of melatonin on activity and expression levels of MMP-2 and MMP-9 in both stem and non-stem ovarian cancer cells." (PMID 29213108, 2017). "Although we could not fine the relationship between FN and MMPs expression in recent study, secreted FN enhances MMP-2 and MMP-9 expression through the MAPK and the PI3-K/Akt-dependent pathways in breast and ovarian cancer cells." (PMID 26637807, 2016). "Stress variables (MDA, AGEs, AOPPs, NO), profile of antioxidants (SOD, Catalase, Vitamin E & A, GSH, GRx, GPx) and inflammatory biomarkers (MMP-9, MMP-2, MMP-11, IL-1α and TNF-α) were biochemically assessed from venous blood of fifty ovarian cancer patients and twenty healthy control subjects." (PMID 27902750, 2016). "Similarly, exosomes of ovarian cancer ascites contain MMP-2, MMP-9 and urokinase-type plasminogen activator (uPa), all of them able to degrade the ECM, facilitating invasion and dissemination of tumor cells." (PMID 26426054, 2015). "Our previous work showed that RhoC could promote the invasion and metastasis of ovarian cancer by affecting VEGF, MMP-9 and ROCK." (PMID 25933027, 2015). "It has been shown that miR-138 may have an effect on tumor metastasis by targeting SOX4 and HIF1a in ovarian cancer and targeting MMP2/MMP9 in cholangiocarcinoma." (PMID 25845814, 2015). "It has been shown that treatment with adrenergic agonists could upregulate the production of matrix metalloproteinase (MMP)-2, MMP-9, and VEGF in ovarian cancer cell lines resulting in increased invasive capability." (PMID 23433478, 2013). "Previous studies indicated that miR-138 may have an effect on tumor metastasis by targeting SOX4 and Hif1a in ovarian cancer, MMP2/MMP9 in cholangiocarcinoma cells and FAK in hela cells." (PMID 24171926, 2013). "Treating ovarian cancer cell lines SKOV3, OVCAR5 and IGROV1 with a PI3K inhibitor, LY294002, there is a reduction in gondatropin-induced MMP-2 activity with little change in MMP-9 activity." (PMID 23591839, 2013). "Here, we observed that minocycline suppressed multistep of ovarian cancer cell metastasis processes including migration, invasion and adhesion ability in a concentration-dependent manner which was coupled with down-regulation of MMP-2 and MMP-9 proteins." (PMID 23593315, 2013). "Whether through a decrease in MMP-2 or MMP-9 activity, inhibiting AKT phosphorylation results in a decrease in invasion, migration, and metastasis of ovarian cancer cells." (PMID 23591839, 2013). "These combined data suggested that by MMP9 inhibition might abolish EGF-HGF induced cellular invasiveness and, therefore, it could be a potential target therapy for ovarian cancer." (PMID 23320251, 2012). "In the pathogenesis of ovarian cancer, MMP-2 and MMP-9 are consistently upregulated." (PMID 22022379, 2011). "The absence of activated MMPs in tumor samples is not unique; this phenomenon was also observed for MMP-9 in ovarian cancer." (PMID 19531263, 2009). "We report that ovarian cancer spheroids secrete much greater amounts of both pro-MMP2 and MMP9 compared to cells grown as a monolayer, and in the case of spheroids, both MMP2 and MMP9 were present in the active form, while monolayer cells only secreted the inactive precursors." (PMID 17567918, 2007).
ovarian carcinoma (continued). "Similarly, icaritin modulates metastasis-related proteins (e.g., MMP-9, E‐cadherin, N‐cadherin, and Vimentin) and exhibits inhibitory effects in multiple myeloma (RPMI 8226 and OPM-2), ovarian cancer (A2780), esophageal cancer stem cells (ECA109) and endometrial cancer (RL95-2 and Ishikawa) cells." (PMID 40490812, 2025). "TNKS inhibition or knockdown reduced ovarian cancer cell proliferation, colony formation, migration, invasion, and tumorigenic potential in nude mice, and these changes correlated with the downregulation of targets (cyclin D1, MDR, and MMP‐9) of Wnt/β‐catenin signalling." (PMID 38898581, 2024). "Furthermore, MMP-9 expression in ovarian cancer was significantly higher than in non-malignant tumors (OR = 11.46, 95 percent CI 8.47–15.50, P0.00001)." (PMID 37833873, 2023). "Among them, MMP9 regulates cell–cell adhesion by catalyzing E-cadherin ectodomain shedding to mediate metastatic dissemination, whereas MMP2 mediates the peritoneal adhesion of ovarian cancer cells by cleaving the extracellular matrix proteins fibronectin and vitronectin into small fragments." (PMID 35860572, 2022). "In addition, the application of CAP-treated solutions to ovarian cancer cells in vitro has been shown to decrease MMP9 but not MMP2 mRNA expression." (PMID 35216069, 2022). "Upregulation of VCAN protein may promote cell motility and the invasiveness of advanced ovarian cancer through activation of the NF-κB signaling pathway and elevated expression of CD44, matrix metalloproteinase-9 (MMP-9), and the hyaluronan-mediated motility receptor." (PMID 35681617, 2022). "Studies have shown that in ovarian cancer cells with high MMP-9 expression, the combined use of MMP9/MMP2 inhibitors and cisplatin could significantly enhance cytotoxicity, confirming that MMP9 is a potential therapeutic target for drug-resistant ovarian cancer." (PMID 33763485, 2021). "Finally, our experiments showed that MIIP could reduce MMP9, which is consistent with the recent report of Rac1/Pak1/p38/MMP axis in ovarian cancer oncogenesis." (PMID 27760566, 2016). "Since the co-expression of EGFR and MMP-9 has prognostic value in cancer, and Neu1 and MMP-9 cross-talk regulates EGFRs in pancreatic cancer cells, we investigated the molecular targeting potential of the Neu1–MMP9 crosstalk platform in human ovarian cancer cell lines in vitro." (PMID 26932374, 2014). "Low BCL9 expression also downregulated the expression of MMP2 and MMP9 in ES-2 cells, suggesting that BCL9 might dissolve the extracellular matrix of ovarian cancer cells by promoting the expression of MMP2 and MMP9, further promoting the invasion and metastasis of ovarian cancer cells." (PMID 31827404, 2019). "Eight polymorphisms (MMP2 C-735T, MMP7 A-181G, MMP8 rs11225395, MMP9 rs6094237, MMP12 rs2276109, MMP20 rs2292730, MMP20 rs12278250, MMP20 rs9787933) were reported associated with ovarian cancer risk, while other polymorphisms could not be associated with ovarian cancer risk." (PMID 28957437, 2017). "More specifically, HK2 by regulating the matrix metalloproteinase 9 (MMP-9) expression, non-processed pseudogene (NANOG), and SRY box transcription factor (SOX)-9 facilitates the metastasis of ovarian cancer (OVC) cells." (PMID 37384249, 2023). "We found that the expression of MMP9 but not MMP2 was markedly altered in both Rap1A overexpression and silencing ovarian cancer cells." (PMID 27925454, 2016). "Pretreatment CD34 mRNA levels were not significantly increased in ovarian cancer patients compared with healthy controls; however, VEGFR2 expression was increased, and plasma levels of VEGF and MMP-9 were also elevated." (PMID 20334653, 2010). "It has also been reported that WFDC4 may stimulate the invasion of ovarian cancer, partly through its antiprotease activity to reduce the releasing of MMP-9, while its role in inducing MMP-9 does not depend on protease inhibitory activity." (PMID 39296934, 2024).